MMP1 (matrix metallopeptidase 1)
Diseases named in the same sentence as MMP1 in open-access papers (continued):
Sharing a sentence is not in itself a finding about the gene and the disease.
tumor (continued). "Additionally, how Mmp1 and the other identified cachectic factors interact in these tumor models to trigger body wasting remains to be determined." (PMID 35319749, 2022). "Then, several bioinformatics tools were utilized to investigate the role of MMP1 in 33 tumor types." (PMID 36727076, 2022). "However, MMP1 rs1799750 and MMP7 rs11568818 were significantly associated with tumor histological grade (p < 0.05)." (PMID 36009438, 2022). "MMP1 expression levels were significantly higher in 19 tumor types than in corresponding controls." (PMID 36727076, 2022). "The results demonstrated that MMP1 had high predictive accuracy (AUC > 0.9) in 15 tumor types." (PMID 36727076, 2022). "MMP1 expression was significantly related to the tumor stage in 9 cancer types." (PMID 36727076, 2022). "Simultaneously, lymph node metastasis promotes factor, vascular endothelial growth factor (VEGF) and matrix metalloproteinase 1 (MMP1), one key enzyme activating extracellular matrix proteolysis during tumor metastasis, have been down-regulated while overexpressing UCP1." (PMID 35541900, 2022). "MMP1 expression was higher in tumor tissues than in control tissues in most tumor types." (PMID 36727076, 2022). "The production of MMP1 is directly dependent on the heterogeneous tumor proteolytic activity." (PMID 33513131, 2021). "Specific inhibitors of MMP-1 suppressed tumor induction in mouse model of colon cancer." (PMID 33833342, 2021). "Analysis with TIMER showed strong correlation between NRP1 expression and the abundance of tumor progression-related genes, MMP1, MMP3, MMP9, VEGFC, FLT4 and CXCL12 in LUSC, while there isn’t clear association between NRP1 expression and this panel of pro-tumorigenic genes in LUAD." (PMID 34168096, 2021). "Expression of MMPs and their endogenous regulators in cervical cancer tumor samples associated with HPV16 showed that the invasive and metastatic potential of the tumor is apparently determined by an increase in the expression of collagenases MMP-1, MT1-MMP, and gelatinase." (PMID 34830452, 2021). "MMP9 may also be associated with metastasis in CRC; high levels of both MMP1 and MMP9 expression in tumor-free mucosa correlated with TNM-stage and lymph node involvement." (PMID 33450835, 2021). "In these cells, JNK promotes the upregulation of MMP1 and the actin cross-linking protein Cheerio necessary for basement membrane degradation and cytoskeleton remodeling, respectively, together leading to tumor cell migration." (PMID 34445578, 2021). "Among all MMP members, MMP-1, 2, 3, 9 and 13 have been reported to correlate with tumor metastasis." (PMID 31882379, 2021). "However, MMP-1, MMP-9 and TIMP-1 were more frequently expressed by stromal macrophages in BCC samples from immunocompetent individuals, emphasizing the role of the tumor microenvironment in BCC behavior in association with the patient’s immune status." (PMID 34204372, 2021). "To assess whether expression of these MMPs and collagen I in combination with LAIR-1 impacts survival, we performed bioinformatic analyses of tumor MMP1, MMP9, COL1A1 and LAIR1 mRNA expression using data from the TCGA database." (PMID 34691040, 2021). "MAPK/Erk and PI3K/Akt pathway were newly identified as the mechanism of MMP1 in tumor promotion." (PMID 34753916, 2021). "Besides, we observe that the MMP1 external front is slightly shifted ahead with respect to the tumor front region." (PMID 33513131, 2021). "Recent studies support a critical role of MMP1/PAR1 axis in tumor development and progression." (PMID 34753916, 2021). "Therefore, inhibiting the expression of MMP-2, MMP-9, and MMP-1 is important to prevent tumor invasion and metastasis." (PMID 33833342, 2021). "MMP-1 was shown to promote tumor growth and chemoresistance." (PMID 34204372, 2021). "The previous considerations about the relative positions of these three elements (GB membrane density, FAK, and MMP1 distribution) might be seen as an indicator of the direction of tumor migration." (PMID 33513131, 2021).
tumor (continued). "Therefore, we propose the localization of MMP1s on TMs and the mathematical modeling of MMP1 dynamics in relation to the tumor front." (PMID 33513131, 2021). "Moreover, in the morphologically normal tissue adjacent to the tumor, significant expression of MMP-1, MMP-2, and MMP-9 was found, which additionally contributes to an increase in the destructive potential of the tumor." (PMID 34830452, 2021). "Moreover, we have investigated the stromal score, immune score, and tumor purity of five subtypes, along with the estimate score of MMP1, MMP2, MMP9, MMP12, MMP13 in five subtypes of BRCA." (PMID 35069702, 2021). "Intriguingly, in many solid tumors, MMPs are produced by tumor stromal cells, rather than by tumor cells, including tumor-associated interstitial collagenase (MMP-1), stromelysin-1 (MMP-3), stromelysin-3 (MMP-11), and gelatinase A (MMP-2)." (PMID 32948029, 2020). "Moreover, SPP1 induces increased PLAU production that indirectly activates MMP1, which promotes tumor progression and LSCC cell migration and invasion." (PMID 33092550, 2020). "Interestingly, the expression of MMP-1 was higher in the 786-O cell line (B), which is derived from a primary ccRCC tumor, when compared to both metastatic ccRCC cell lines (C and D)." (PMID 32610589, 2020). "In contrast, inhibition of EV-mediated MMP1 secretion decreases tumor invasiveness." (PMID 33126572, 2020). "All these data suggest that degradation capacity of MMP1 and other metalloproteases, which cleave several components of the extracellular matrix, could contribute to promoting tumor spread via the lymph nodes." (PMID 33396463, 2020). "Furthermore, the molecular mechanisms that induce MMP1 expression to grant tumor cells a higher brain invasive phenotype remain poorly understood." (PMID 33002044, 2020). "MMP1 also has been reported to promote tumor invasion and metastasis via loosening cell adhesion." (PMID 33046043, 2020). "Given that high ROS potentiates JNK-dependent MMP1 induction, most of the RNAi lines tested (ATPsynβ-RNAi, sdhC-RNAi and cox5A-RNAi) need to be accompanied by simultaneous overexpression of ROS scavengers in order to reduce Hipk tumor growth." (PMID 33199523, 2020). "MMP-1 can degrade a broad range of substrates and contribute to tumor growth and tumor formation." (PMID 33553142, 2020). "Due to its important role in tumor metastasis, MMP-1 represents a potential pharmacological target." (PMID 33002044, 2020). "MMP1 is responsible for degrading basement membrane proteins and facilitating tumor invasion." (PMID 33199523, 2020). "Therefore, we evidentially show that ETV4 promotes tumor progression by transcriptionally regulating MMP1 in PTC cells." (PMID 32982961, 2020). "Taken together, these results indicate that SSO and its active compound acacetin can prevent UVB-induced MMP-1 expression, which leads to skin photoaging, and may therefore have therapeutic potential as an anti-wrinkle agent to improve skin health." (PMID 32522955, 2020). "MMP-9 is one of the most important MMPs involved in tumor invasion and metastasis, whereas MMP-1 has also been reported to activate endothelial PAR-1 to facilitate endothelial permeability and transendothelial migration of tumor cells, and thus to promote metastatic dissemination." (PMID 30483898, 2019). "Moreover, immunofluorescence analysis further confirmed the expression of MMP-1 in LSCC with a gradual increase with the tumor growth." (PMID 31275143, 2019). "Recently, MMP1 has been implicated as a promoter of angiogenesis and in the context of tumour sensitivity to CRT, neovascularisation, vascularity and hypoxia are all factors that significantly influence tumour response to therapy." (PMID 31391080, 2019). "MMP-1 is highly expressed by BC tissues and some authors have found that it may have an effect on the tumor microenvironment." (PMID 31726667, 2019).
tumor (continued). "Moreover, CAPE-mediated inhibition of MMP-1 displayed similar effects compared to that of retinol, a commonly used anti-skin wrinkle agent and well-known MMP-1 inhibitor." (PMID 31234539, 2019). "Many investigators have screened molecules that are overexpressed during tumor progression as target molecules for therapeutic drugs and have attempted to prevent tumor progression by inhibiting their activity or suppressing the expression levels of these tumor-promoting molecules, such as MMP-1." (PMID 31014014, 2019). "The reason for this is not known, but it may be that peritoneal tissue undergoes a process involving MMP-1 that prepares tissues for tumour invasion." (PMID 29623449, 2018). "On the other hand, overexpression of MMP-1 leads to tumour progression and metastasis." (PMID 30423799, 2018). "Furthermore, highly tumor‐tropic MSCs expressed higher levels of MMP‐1 and insulin‐like growth factor (IGF)‐2 than poorly migrating MSCs." (PMID 29321953, 2018). "The authors suggested that MMP-1 generates a fibrous stroma that aids invasion of the tumour." (PMID 29623449, 2018). "This is supported by the local presence of MMP-1 in the peripheral zone of tumour-invaded areas." (PMID 29623449, 2018). "The results showed that total pro‐MMP‐1 protein expression and its corresponding MMP‐1 activity were higher in MSCs with greater tumor‐tropic potential in comparison with the poorly migrating MSCs, suggesting possible crosstalk between MMP‐1 and IGF‐2 signaling." (PMID 29321953, 2018). "In the microscopically tumour-free areas, a more general expression of MMP-1 was seen." (PMID 29623449, 2018). "Our data demonstrated that MMP‐1 secreted by highly tumor‐tropic MSCs could act as IGFBP2 proteinase, resulting in cleavage of the IGF‐2/IGFBP2 complex followed by the extracellular release of free IGF‐2." (PMID 29321953, 2018). "Moreover, transcript levels of mmp1 in the cephalic complex were also found to be upregulated in Notchact/lgl-IR tumor as compared to that of the controls." (PMID 29661224, 2018). "Additionally, we observed ectopic expression of Matrix metalloprotease 1 (MMP1), which is required for matrix degradation and the invasive potential of tumor cells." (PMID 29560857, 2018). "Matrix metalloproteinase 1 (MMP-1) gene, located on the long arm of chromosome 11 (11q22.3), is expressed in various cells, such as chondrocytes, fibroblasts, epithelial and endothelial cells, and tumor cells." (PMID 30177524, 2018). "Immunohistochemical staining of these proteins in biopsies from human OvCa peritoneal implants showed mesothelial‐derived (calretinin‐positive) spindle‐like cells in the stroma tissue surrounding tumour nodules, overlapping with areas with marked staining for MMP1, IL‐33, EGR1, TSP1, and GREM1." (PMID 28247413, 2017). "Given that miR-361-5p downregulated FGFR1 and MMP-1 in BC cells to suppress tumor progression, we next explored whether this relationship existed in clinical samples." (PMID 29132384, 2017). "The other variables like stage of cancer, histological type of tumor, ER/PR status, lymph node status and metastasis status have not revealed any significant association with MMP-1–1607 1G/2G polymorphism." (PMID 28961241, 2017). "However, a recent study has shown that hypomethylating agents enhance tumor cell invasion and metastasis through a transcription-dependent modulation of matrix metalloprotease-1 (MMP-1) expression." (PMID 28947962, 2017). "The mean intensity of Mmp1 staining in GFP-labelled tumours was also reduced 5.1-fold (P<0.001)." (PMID 28346426, 2017). "Furthermore, JNK partly mediates the expression of MMP1 (Matrix metalloprotease 1), which can facilitate cell motility and the degradation of the basement membrane, which are both related to tumor malignancy potential." (PMID 27121062, 2016). "Because MMP1 can function as an oncogene and free MMP1 proteins can be released into blood from tumor cells, MMP1 could possibly be used as a non-invasive biomarker of ESCC." (PMID 27436512, 2016).
tumor (continued). "Our results suggest that elevated expression of MMP1 in vivo promotes tumour development, and we hypothesised that this may be via regulation of various cells within the tumour microenvironment (fibroblasts and endothelial cells)." (PMID 27324842, 2016). "Thus, overexpression of MMP-1 correlates positively with tumor aggressiveness and a poor clinical outcome." (PMID 27271600, 2016). "MMP-1 interacts with the tumor cell surface through an extracellular matrix metalloproteinase inducer (EMMPRIN), suggesting that the binding and activation of MMP-1 by EMMPRIN may be a significant step in the development of aggressive tumor cells." (PMID 25664615, 2015). "ERK activation can increase MMP1 which can cause ECM degradation and tumor invasiveness." (PMID 25699081, 2015). "Co-cultures of HFs and MG-63 cells showed high levels of MMP1 after only 24 h and they greatly increased up to 96 h, suggesting a strong influence of the tumor microenviroment on the upregulation of the matrix metalloproteinases responsible for the disruption of the ECM and tumor invasiveness." (PMID 24883044, 2014). "The aim of this study was to assess correlation between CTCs and tumor MMP1 in BC." (PMID 24972610, 2014). "An overexpression of MMP1 has been described in many types of human tumor tissues." (PMID 24883044, 2014). "In addition to other tumor-derived cytokines that can act as circulating tumor cell attractants, MMP-1 was shown to be a key mediator of such primary tumor invasion." (PMID 24518611, 2014). "MMP1 cleave extracellular matrix components and thus play an important role in tumor invasion." (PMID 24972610, 2014). "Interestingly, experimental depletion of UEV1 in MDA-MB-231 cells reduces MMP1 expression and prevents tumor formation and metastasis in a xenograft mouse model, while overexpression of MMP1 overrides the metastasis effects in UEV1-depleted cells." (PMID 25022892, 2014). "It has been suggested that the thymidine degradation products 2-deoxy-d-ribose-1-phosphate and 2-deoxy-d-ribose are sources of free radicals, and that this oxidative stress increases the production of the angiogenic factors IL-8, VEGF, and MMP-1 by tumour cells." (PMID 25350954, 2014). "Tumor cells showed a greater expression of MMPs and TIMPs than stromal cells except for MMP-1." (PMID 25510449, 2014). "This suggests that the small tumor size in MMP-1 and MMP-13 knockdown mice could be due to low cell proliferation." (PMID 25527274, 2014). "We also correlated MMP1 expression with other patients’ tumor characteristics." (PMID 24972610, 2014). "Thus, overexpression of MMP1 or MMP2 has been shown to be necessary to form lung metastasis by breast tumor cells and expression of specific proteases is a hallmark of many tumor types." (PMID 24243807, 2013). "MMP-1 is critical in degrading interstitial collagen, and tumor cells may require that function to invade." (PMID 25339983, 2013). "In parallel, upon RUNX2 knockdown, we have observed a predominant and strong downregulation of gene nodes known to be implicated in EOC tumorigenesis (PTGS1/COX1, FGF2, IL1A, Sapk, C/ebp, SELE, UBQLN1, PSAT1, ALDH1A1, GDF15, MTHFD2), including EOC tumor invasion/metastasis (MMP1, MMP13, Creb);." (PMID 24124450, 2013). "The discovery that silencing of mmp1 expression leads to degradation of the basement membrane and triggers unregulated tissue invasion in intact animals supports the possibility that this protease plays protective/tumor-suppressive roles." (PMID 23405188, 2013). "Immunohistochemical staining of MMP1 revealed a reduced positive signal in tumor xenografts and pulmonary metastatic lesions generated from AEG-1-knockdown HNSCC cells, as compared to the cytosolic and juxtacellular staining of MMP1 observed in lesions arising from control cells." (PMID 24063540, 2013).
tumor (continued). "Increased expression of MYB found in the tumor vs mets comparison (logFC 1.2) may also contribute to MMP1 down-regulation; Myb protein is known to up-regulate cathepsin D and MMP9 and down-regulate MMP1." (PMID 23405235, 2013). "It was discovered in the MMP-1 promoter as being activated by tumor promoting phorbol esters." (PMID 25339983, 2013). "Of the three genes found with significantly augmented expression in cocultures, two were proteases (MMP1 and MMP9), whose elevated expressions in the tumor microenvironment are associated with tumor cell invasion through increased degradation of ECM components." (PMID 23762835, 2013). "The array analysis showed that direct co-culture with MDA-MB-231 tumour cells led to an increase in the expression of matrix metalloprotease 1 (MMP1) in CCD-1068SK fibroblasts relative to CCD-1068SK mono-cultures while the expression of a number of collagen genes was down-regulated." (PMID 24090133, 2013). "KS cells are known to express high levels of MMP-1, -2, -3, -7, -9, -13, -19, and previous reports suggest that some of these metalloproteinases may contribute to the invasive phenotype of the tumour." (PMID 24244164, 2013). "How MMP-1 function is coopted by tumor cells is an open question." (PMID 25339983, 2013). "MMP-1 collagenase is primarily responsible for cleaving type I collagen found in the tumor stroma." (PMID 23342250, 2012). "To test whether MMP-1 knockdown affected tumor growth in vivo, we injected MMP-1 shRNA expressing cells and control shRNA expressing cells into the mammary fat pads of nude mice." (PMID 23217186, 2012). "MMP-1 positivity in tumour cells and in stromal cells was observed in all analyzed tumours." (PMID 21835023, 2011). "The MMP-1 expression in tumour cells ranged from 10% to 95% and in stromal cells from 5% to 80%." (PMID 21835023, 2011). "It has been reported that both NFκB and AP-1 binding sites are present in the promoter region of MMP-1 and enhanced production of MMP-1 is associated with a more aggressive tumor growth, a higher metastatic potential, and poor clinical outcome of malignant tumors." (PMID 21637790, 2011). "In our study, the expression of MMP-1 both in tumour cells and in stromal cells and especially the correlation between the expression and tumour grade may indicate an impact of MMP-1 on cellular properties such as growth, death, and migration." (PMID 21835023, 2011). "Both MMP-1 and uPA have demonstrated roles in facilitating invasion and metastasis of cancer cells, presumably via degradation of the basement membrane surrounding the tumor." (PMID 21595984, 2011). "Our results showed a higher MMP-1 expression in tumour cells than in stromal cells." (PMID 21835023, 2011). "In addition to the cell-lines, four primary GBM cell cutures, which were derived from patient's tumor samples, were analysed for MMP-1, -8, -9, -10, -11, -13, -17, -19, -23, -24 and MMP-28 mRNA expression by semiquantitative RT-PCR." (PMID 21067565, 2010). "MMP1 gene expression was detectable largely in the tumor cell population (p = 0.05)." (PMID 21170377, 2010). "95% (n = 39/41) of the patients with BE and adjacent EAC expressed MMP-1 within the tumor." (PMID 20946664, 2010). "The effect of MMP1 overexpression on MSC tumor-tracking ability was further confirmed in vivo." (PMID 19489099, 2009). "MMP1 overexpression is the most promising marker, and its detection could help identify tumor cells in tissue or saliva." (PMID 19835631, 2009). "Conversely, exogenous expression of MMP1 in poorly migrating MSCs could reconstitute the tumor trophic abilities of these cells in vitro and in vivo." (PMID 19489099, 2009). "It has been shown that MMP-1 is actively secreted by tumor cells." (PMID 18954439, 2008). "Furthermore, MMP1 expression has been found to be an important marker of metastasis in breast cancer cells, confirming the importance of MMPs in tumor growth and invasion." (PMID 19094243, 2008).